STIM1 (stromal interaction molecule 1)
Diseases named in the same sentence as STIM1 in open-access papers (continued):
Sharing a sentence is not in itself a finding about the gene and the disease.
tumor (continued). "The possible oncogenic role of STIM1 is through regulation of SOCE activity, a major modulator of tumor migration and invasiveness, neovascularization, antitumor immunity, inhibition of apoptosis, and induced hypoxia pathways." (PMID 38532463, 2024). "Recently, the small molecule drug that target STIM1-mediated SOCE have been developed and showed an anti-tumor effect." (PMID 37542345, 2023). "Abnormally expressed STIM1 disrupts the dynamic balance of intracellular Ca2+ by enhancing the SOCE activity, thus triggering the malignant transformation of tumor cells, such as the switch from E- to N-cadherin shown in our study." (PMID 36677874, 2023). "In HCC cell lines (e.g., Huh-7 and HepG2), TRP channels can also interact with Orai1 and STIM1, thus contributing to SOCE regulation and promoting tumour proliferation." (PMID 35269437, 2022). "In two STIM1 knockout cell lines (SMMC7721 and HepG2), tumour invasion and proliferation were significantly inhibited." (PMID 35269437, 2022). "STIM1-mediated cytosolic Ca2+ entry by the SOCE mechanism stabilizes HIF-1α via CaMKII-mediated p300 activation, thus promoting tumour proliferation." (PMID 35269437, 2022). "Hypoxia and intracellular Ca2+ transients are the basic characteristics of tumors, signaling cascades initiated or regulated by HIF-1 are critical for the process of tumorigenesis, and STIM1 mediates SOCE activation and promotes tumor invasion and migration." (PMID 36187789, 2022). "Together, a regulatory circuit consisting of the STIM1-mediated SOCE mechanism and phosphorylated p300-stablized HIF-1α can promote tumour proliferation under hypoxic conditions." (PMID 35269437, 2022). "To analyze the effects of STIM1 knock-down on tumor growth in vivo, we transplanted MOCK and STIM1-KD ML-1 cells into the zebrafish embryos." (PMID 34155535, 2021). "The simultaneous STIM1 and STIM2 immunostaining showed that, despite the overexpression of both isoforms in tumor tissues, STIM1 is the principle ER Ca2+-sensing molecule detected in the invasive tumor front." (PMID 35008759, 2021). "We subsequently examined the effect of exosomal miR-145 from STIM1-KO-MDA-MB-231 cells on the IRS1 pathway, which is the key pathway regulating tumor angiogenesis." (PMID 33414420, 2021). "Our study shows that GSC from patient-derived surgical tumor specimen express Orai1 and TRPC1 as well as STIM1, as do the adult neural stem cells from which GSC originate, at least in part." (PMID 34298643, 2021). "Increased expression of STIM1 was also observed in HCC tumors in mice and in samples of human HCC tissue compared with non-tumor tissue." (PMID 32987945, 2020). "STIM1 and HIF-1α protein levels were also upregulated in some PDAC tumor samples compared to non-tumor samples." (PMID 33178018, 2020). "Not only the main players of SOCE, STIM1 and Orai1, but also the slightly “neglected” STIM2 and Orai3 are involved in proliferation and growth of tumor cells." (PMID 30935064, 2019). "Five potential target genes including STIM1 and GNAO1 were found, and their gene expression was significantly decreased in tumor samples." (PMID 31569550, 2019). "The increase in STIM1 expression is a consequence of a direct HIF-1α binding to the promoter of STIM1 and leads to an increase in SOCE in HCCs promoting tumor growth." (PMID 30935064, 2019). "Deletion or abnormal expression of STIM1 and ORAI1 leads to congenital unprogressive myopathy, coagulopathy, T and B cell dysfunction and also affects tumor cell growth and invasion." (PMID 31426853, 2019). "Overexpression of STIM1 and ORAI1 enhances the ability of some tumor cells to resist apoptosis, but leads to apoptosis of other tumor cells." (PMID 31426853, 2019). "The migration and the invasion processes of tumor cells can be regulated by many factors, such as BRMS1, E-cadherin, CXCL12, MMP9, Orai1, Stim1, TGF-β, and VEGF." (PMID 29316690, 2018).
tumor (continued). "Therefore, Stim1 and Orai1 may be also activated in resting, i.e. not stimulated, tumor- and tumor-associated cells, thereby mediating a constitutive influx of Ca2+." (PMID 30123430, 2018). "In tumour cells chorein up-regulates ORAI1, a Ca2+-channel accomplishing store operated Ca2+-entry (SOCE) upon stimulation by STIM1." (PMID 28743945, 2017). "STIM1- and STIM2-mediated store-operated calcium entry in CD8+ T cells is crucial for anti-tumor immunity." (PMID 25695601, 2015). "Further studies revealed that the ectopic expression of STIM1 and ORAI1 inhibits tumor cell growth and promotes cell senescence." (PMID 26257076, 2015). "On the one hand, STIM1 overexpression promotes the EMT and thereby enhances cell migration; on the other hand, STIM1 overexpression accelerates tumor cell senescence and modulates the tumor immuno-microenvironment." (PMID 26257076, 2015). "In our previous study on CRC, STIM1 overexpression increased CRC aggressiveness, COX-2 gene activation and promoted tumor progression." (PMID 26543234, 2015). "Of note, this paper provides some theories about the individual importance of STIM1 and STIM2 in cytotoxic T-cell function against tumour cells." (PMID 24000152, 2013). "Taken together, our results show for the first time that activation of CRAC channels by STIM1 and STIM2 proteins is essential for tumour immunosurveillance by CD8+ T cells." (PMID 23922331, 2013). "STIM1 and STIM2 are dispensable for the priming, expansion and homing of tumour antigen-specific CTLs." (PMID 23922331, 2013). "In this view, Stim1, Orai1, and TRPC1 stand out as very promising molecular identities to hit to adverse tumor neovascularization." (PMID 23049731, 2012). "STIM1, a type I transmembrane protein characterized by its extracellular N-terminal domain (STIM1PM), was initially identified as a plasma membrane (PM)-localized protein with tumor growth suppressor activity." (PMID 41792344, 2026). "Furthermore, our findings are consistent with prior studies showing that SOCE components, such as STIM1 and Orai1, are upregulated in HCC and promote tumor progression." (PMID 40362663, 2025). "Moreover, xenograft tumor models and clinical specimens further identified the oncogenic role of TSPAN18 mediated by its positive regulation of STIM1." (PMID 37542345, 2023). "Phemindole treatment reduces STIM1 expression by reducing the interaction between STIM1 and Orai1, resulting in decreased cell migration in vitro through the regulation of FAK; a reduction in tumor growth in vivo was also observed." (PMID 36982380, 2023). "We conducted similar regression tests for STIM1 scores derived from diverse non-malignant cell types, while using TCGA samples without filtering for tumor purity (sample no. = 471)." (PMID 33859736, 2021). "In spite that STIM2 protein expression does not change with DFMO, the ratio STIM1/STIM2 is indeed reduced by DFMO treatment consistently with reversal of the tumor phenotype." (PMID 30642111, 2019). "Mechanistically, STIM1 and STIM2 are crucial for the cytolytic effector functions of CTLs, especially the production of IFN-γ and TNF-α, the release of perforin-containing cytolytic granules, the induction of FasL, and thus tumor cell killing." (PMID 31252656, 2019). "We demonstrated that targeting HSP27 selectively affects STIM1, which regulates and coordinates Ca2+ entry into the tumor cells, but not Orai1." (PMID 30544747, 2018). "Our clinical studies showed that approximately 89% of HNSCC display STIM1 overexpression in tumor tissues and had close linear relationship with tumor sizes but not with neck lymph node metastasis." (PMID 28494008, 2017). "The invasion of tumor cells could be regulated by many factors such as BRMS1, E-cadherin, Keratin19, LOXL2, MMP9, Orai1, Stim1, TGF-β and VEGF." (PMID 27008697, 2016). "In our study, we found an increased expression of Orai1 and STIM2 but not STIM1 in ESCC tumor tissues." (PMID 25481035, 2015).
tumor (continued). "Increasing evidence indicates that STIM1-mediated cyclooxygenase (COX)-2 overexpression, an important inducible proinflammatory enzyme, might exacerbate tumor migration and progression." (PMID 26543234, 2015). "Interestingly, STIM1, the Ca2+ sensor for the activation of the SOC influx, had been reported as an oncogene or a tumor suppressor gene by different groups." (PMID 25977921, 2015). "In addition, immunofluorescent staining of E-cadherin was decreased in tumor tissues that were removed from mice grafted with DU145-STIM1-YFP and DU145-STIM1-YFP-ORAI1, further demonstrating that STIM1 promotes the EMT in vivo." (PMID 26257076, 2015). "An unexpected finding in the present study was the observed increase in Orai1 expression with no increase in STIM1 expression in ESCC tumor tissues." (PMID 24797725, 2014). "The sustained Ca2+ release required for the nuclear translocation of NFAT and its subsequent regulation of FasL expression lends support to the theory that intact SOCE as regulated by STIM1, STIM2, Orai1 can have transcriptional effects that affect the function of cytotoxic T cells against tumours." (PMID 24000152, 2013). "Therefore, STIM1 and SOX2 co-expression in tumor cells and intra-tumoral stroma could contribute to the development of PDAC and AAC." (PMID 38532463, 2024). "In addition, our findings indicate that STIM1 is significantly upregulated in tumor tissue compared to normal tissue in HCC patients, which is consistent with our previous study." (PMID 38344399, 2024). "Rationale: Previous studies have implicated the functions of stromal interaction molecule 1 (STIM1) in immunity and malignancy, however, the specificity and effects of STIM1 expression in malignant and non-malignant cells in the tumor microenvironment are unclear." (PMID 33859736, 2021). "Moreover, we gave an integrated view of how malignant-cell-expressed STIM1 exerts its biological functions and mediates downstream cellular programs in diverse non-malignant cell types in the tumor microenvironment." (PMID 33859736, 2021). "In this context, new hopes arose from a recent study demonstrating that knockdown of STIM1 (stromal interaction molecule 1) in TC cells restored NIS expression and significantly improved iodine uptake, sensitized cells to chemotherapeutic drugs, and significantly reduced xenograft tumor growth." (PMID 34771729, 2021). "However, comparing between STIM1 overexpression and STIM1 low-expression groups of READ patients did not reveal dysregulation of the SOCE pathway, unraveling a minor role of STIM1 and the SOCE pathway in ROAD tumor dissemination." (PMID 26543234, 2015). "It was found that mice lacking STIM1 and STIM2 in CTLs fail to adequately control tumor cell engraftment and growth in vivo." (PMID 31252656, 2019). "Accordingly, CD8+ T cells lacking STIM1 and STIM2 failed to kill tumour cells both in vitro and in vivo." (PMID 23922331, 2013). "SOCE in cytotoxic CD8+ T cells was essential to control the engraftment of tumour cells as only wild-type CD8+ T cells but not those lacking STIM1 and STIM2 prevented tumour growth." (PMID 23922331, 2013). "Since the expansion and tumour infiltration of CTLs is independent of STIM1 and STIM2, we speculated that cytolytic effector functions of tumour-specific CD8+ T cells may require SOCE." (PMID 23922331, 2013).
myopathy (27 papers, 2011 to 2025). A disease of the muscle in which the muscle fibers do not function properly. "TAM was originally described as a myopathy associated with gain of function mutations in STIM1 and ORAI1, the two key proteins participating in the SOCE mechanism." (PMID 39126637, 2024). "While tubular aggregates are associated with STIM1 mutations, it remains to be determined if they are required for STIM1 myopathy." (PMID 38300705, 2024). "This study describes a novel STIM1 mutation in a child with severe lymphoproliferation, recurrent infections, myopathy, iris hypoplasia, and enamel hypoplasia." (PMID 38578569, 2024). "In the present work, we provide evidence that a gain-of-function mutation in the STIM1 gene is sufficient to induce a progressive myopathy accompanied by minor changes in Ca2+ signaling and drastic changes in nuclear structure and function." (PMID 38300705, 2024). "This review focuses on several rare conditions associated with STIM1 mutations that lead to either gain- or loss-of-function, characterized by myopathy, hematological and immunological disorders, among others, and due to abnormal activation of CRACs." (PMID 37759684, 2023). "Abnormal N-linked glycosylation of STIM1 and Orai1 has been observed in a variety of pathologies, including myopathies with tubular aggregates or septic myocardial depression." (PMID 36612199, 2022). "Accordingly, these data suggest that RYR1 should be considered for genetic analysis in a myopathy with TA where STIM1, ORAI1 and CASQ1 mutations have been excluded." (PMID 35666680, 2022). "These experiments show that STIM1 mutations that cause tubular aggregate myopathy result in constitutive activity and have a robust stimulatory effect on autophagosome formation and autophagy transcription factors." (PMID 32575830, 2020). "Patients with a loss-of-function mutation of STIM1, E136X, show congenital myopathies as well as severe combined immunodeficiency." (PMID 29263348, 2017). "In addition, a novel pathway was implicated in myopathies with the discovery of pathogenic variants in STIM1, ORAI1, and CASQ1 that are key players of Ca2+ homeostasis through the SOCE mechanism." (PMID 38982518, 2024). "Despite the different location of STIM1 gene mutations, and the small number of patients reported this pattern of muscle involvement is common indicating in muscle MRI a valuable tool for diagnosis of this rare myopathy." (PMID 37155641, 2023). "Not only are they present in muscle biopsies from patients with mutations in proteins involved in the glycosylation pathway but are also implicated in myopathies resulting from STIM1 and ORAI1 mutations, and are present in muscle from Caveolin1−/− and Caveolin2−/− mice." (PMID 29905857, 2018). "Finally, we discuss the phenotypes and the pathomechanism of myopathies caused by mutations in the STIM1 and ORAI1 genes." (PMID 27879676, 2016). "However, this diagnosis should be considered in patients presenting proximal dominant leg weakness, which may be confused with other types of muscular dystrophy or inflammatory myopathy in most cases of STIM1 or ORAI1 mutations." (PMID 27879676, 2016). "Future work will help to further enhance our comprehension of the mechanisms underlying TAM development and the potential role of STIM1 and ORAI also in other myopathies." (PMID 39126637, 2024). "Gain-of-function mutations in STIM1 and ORAI1 are linked to tubular aggregate (TA) myopathy, a disease characterized by the atypical accumulation of tubes of SR origin." (PMID 39200116, 2024). "A novel homozygous exon 2 deletion in STIM1 was detected in a 3-year-old girl with severe lymphoproliferation, recurrent infections, myopathy, iris hypoplasia, and enamel hypoplasia." (PMID 38578569, 2024). "More cases and evidence are necessary to clarify the dual role of STIM1 in immune system dysregulation and myopathy." (PMID 35812399, 2022).
myopathy (continued). "The conditional deletion of STIM1 in skeletal muscle is prenatally lethal in mice due to myopathy and defective muscle differentiation." (PMID 29263348, 2017). "Congenital non-progressive myopathy in humans is associated with a loss of STIM1 and Orai1 in agreement with findings in vivo and in vitro where loss of STIM1 resulted in muscle differentiation defects." (PMID 28018901, 2016). "These nonimmunological effects, also observed in an unrelated R2524C patient, partially overlap with the dental enamel formation defects and myopathy in ORAI1 and STIM1 patients, although the latter phenotypes are congenital and nonprogressive." (PMID 36302985, 2023). "A significant amount of dysfunctional STIM1 and ORAI1 was accumulated in TAs, representing peculiar assembly of SR tubes; this was found in ageing and in several myopathies." (PMID 34201319, 2021). "At the time of study GMPPB and STIM1 were recently identified myopathy genes and therefore their testing was not yet part of routine diagnostic screening." (PMID 28877744, 2017). "Strikingly, a congenital, nonprogressive myopathy is consistently observed in infant patients, indicating that STIM1 not only plays a crucial role in T-cell activation and proliferation, but also in skeletal-muscle function and/or development (see part 3)." (PMID 21798093, 2011). "In addition, the relative importance of STIM1 versus STIM2 for SOCE in human muscles and their contribution to myopathies may differ among human and mice." (PMID 21798093, 2011).